SMAD2 (SMAD family member 2)
Diseases named in the same sentence as SMAD2 in open-access papers (continued):
Sharing a sentence is not in itself a finding about the gene and the disease.
tumor (continued). "The mechanistic studies further showed that miR-27a-mediated tumor suppressor could be through targeting SGPP1, Smad2 and STAT3." (PMID 25166914, 2014). "Unlike the dual effects of TGF-β, Smad2 has inhibitory effects on both early tumor growth and later malignant conversion." (PMID 25170969, 2014). "Using shRNA knockdown, we found that Smad3 but not Smad2 mediates the TGF-β-induced tumor suppressive responses in M3 tumors, and this tumor suppressive effect of Smad3 was lost in the more malignant M4 cell line." (PMID 24890385, 2014). "Some of the miRNAs with recently identified targets in vitro in various tumor settings other than GIST include: miR-132 targeting Rb1, miR-193b targeting CCND1 and Mcl-1, miR-455-3p targeting Smad2, miR-125b targeting Mcl-1 and Bcl-2 and miR-542-5p targeting survivin." (PMID 23717541, 2013). "However, tumor cells retain a partial ability to respond to the TGF-β signal by further activating some of these pathways, like AKT in the B-CPAP and SMAD2/3 in the TPC1." (PMID 24069422, 2013). "Since several key genes in the pathway were overexpressed in tumor tissues, including TGFB2, TGFBR1, SMAD2, and SMAD4, TGFβ signaling pathway may be involved in the pathogenesis of fibroblastic meningioma." (PMID 23285163, 2012). "Smad1 but not Smad2/3 protein levels were significantly decreased, suggesting that endoglin plays a role in the attenuation of endothelial tumor growth and tumor angiogenesis." (PMID 23209720, 2012). "To demonstrate whether the activation of Smad2/3 and p38 is specific to TGF-β signaling triggered by tumor exosomes, we blocked TGF-β signaling pathway with TGF-β R1inhibitor and detected the levels of phosphorylated Smad2/3 and p38." (PMID 23285052, 2012). "TGFβ is well documented as an inducer of EMT and a potent stimulator of angiogenesis, however, neither TGFβ nor its target VEGF, which are usually elevated in tumor cells and contribute to angiogenesis and tumor metastasis, is increased in K5.Smad2-/- SCC." (PMID 22204491, 2011). "In TMV-treated Treg, increased expression levels of phospho-STAT3 and phospho-SMAD2/3 and of IL-10 and TGF-β1 expression as well as production may be responsible for attenuating anti-tumor immune responses in cancer patients." (PMID 20661468, 2010). "Three candidate tumour suppressor genes, DCC, SMAD4 and SMAD2, map to this region." (PMID 10993648, 2000). "Furthermore, the suppression of other CDKIs by SMAD2/3-NANOG-OCT4-EZH2-SNON in hPSCs could also support the proliferation capacity of cancer stem cells, considering the tumor-promoting effects of SNON." (PMID 38758030, 2025). "For example, piR-25783 activates the TGF-β/Smad2/Smad3 pathway in fibroblasts by increasing Smad2 and Smad3 phosphorylation, promoting the fibroblast-to-myofibroblast transition (FMT) process and enhancing the proliferative and metastatic properties of tumor cells." (PMID 38915084, 2024). "Western blotting of tumor samples showed that the combination treatment with CQ increased heat treatment induced the accumulation of LC3-II and cleaved-caspase 9, and retarded heat treatment induced the up-regulation of TGF-β2, Smad2 phosphorylation and N-cadherin and down-regulation of E-cadherin." (PMID 36650834, 2023). "Moreover, immunostaining analysis further demonstrated that recurrent patients exhibited enhanced Smad2/3 expression in tumor tissues, when compared to non-recurrent patients, indicating the potential role of Smad2/3 in TRIM9-assocaited tumor progression." (PMID 37249822, 2023). "However, the miR-23b-3p/miR-24-3p-mediated SMAD2 expression decrease occurred only at the translational level, but not the transcriptional level, suggesting that CASC15 utilized another approach to regulate SMAD2 mRNA expression, which also contributed to CASC15's tumor-promoting role." (PMID 35342355, 2022).
tumor (continued). "Notably, PZH has exhibited therapeutic efficacy against tumor metastasis and EMT by targeting the TGF-β/Smads signaling pathway, resulting in a decrease in N-cadherin, TGF-β, p-Smad2/3, and Smad4 expressions, while an increase in E-cadherin expression in vitro and in vivo." (PMID 35308223, 2022). "Moreover, the protein expression p-Smad2/3 and a-SMA of tumor tissue in Rg3-Lp and Rg3-Lp/DTX group was obviously lower than that in C-Lp/DTX group, indicating that Rg3 can effectively inhibit the conversion to CAFs via tumor TGF-β secretion and TGF-β/Smad signaling suppression." (PMID 36109762, 2022). "Herein, tumor growth between HFD-fed obese and ND-fed lean mice was closely related to elevated circulating WBCs, lymphocytes, neutrophils, plasma levels of soluble P-selectin, TGF-β1 and HMGB1, as well as increased tumor expressions of HMGB1, RAGE, Smad2/3 phosphorylation, CD62P and MPO." (PMID 36012397, 2022). "Therefore, conversely, one of the reasons for the invasivity of this type of tumor may be that S100A11 induces phosphorylation of SMAD2/3 through TGF-β, which then accelerates the process of tumor cell migration, tissue infiltration, and EMT." (PMID 34179021, 2021). "Ligation of Dex and glucocorticoid receptor (GR) on tumor cells activated the PI3K signaling pathway and upregulated serum glucocorticoid-inducible kinase 1 (SGK1) expression, and then increased the expression of connective tissue growth factor (CTGF) through Nedd4l-Smad2." (PMID 34272474, 2021). "Unlike Smad2 and Smad4, Smad3 nuclear localization is diminished in tumor samples." (PMID 34501347, 2021). "Mechanistically, tranilast facilitated ECM remodeling by reducing TGFβ1 expression, thereby inhibiting Smad2/3 phosphorylation, and suppressing TGFβ-mediated expression of COL1A1, connective tissue growth factor (CTGF), and hyaluronan synthase 2 (HAS2) in MCF10CA1a tumor xenografts." (PMID 33391538, 2021). "Similarly, tumor cells’ glucose uptake and lactate production with and without Smad2/3 knockdown also showed opposite results under normoxic and hypoxic conditions." (PMID 34930376, 2021). "In conclusion, DDX39B acts as a tumor promoter in CRC by upregulating the expression of FUT3 and then promoting the fucosylation of TGFβR-I, which subsequently enhances activation of the TGFβ/SMAD2 signaling pathway to facilitate the invasion and metastasis of CRC." (PMID 33436563, 2021). "Previous studies have already proved the regulation function of SMAD2, SMAD4, and TGFBR2 in cancers, and these genes were also found related with miRNAs that strongly correlated with tumor features, indicating the potential function and clinical utility in immunotherapy." (PMID 34722540, 2021). "However, Smad2/3 phosphorylation levels and the expression of ECM-associated genes were measured in tumor tissues rather than CAFs." (PMID 33391538, 2021). "Based on the mass spectra from tumour specimens, our discriminant algorithm calculated the results in each dissected tumour area and predicted that the marginal tumour areas contained more HNSCC cells with high p-SMAD2 levels than the central tumour areas of HNSCC tissue." (PMID 32020064, 2020). "Indeed, TGF-β is directly involved in CD103 expression in tumor-specific T cells upon engagement of TCR with specific tumor peptide–MHC-I complexes, through binding of Smad2/3 and NFAT-1 transcription factors to promoter and enhancer elements of the ITGAE gene, which encodes the CD103 (αE) subunit." (PMID 30158938, 2018). "Indeed, LY treatment significantly reduced the phosphorylation of T220/T179, irrespective of Smad2/3 activation, but had negligible effects on the other linker serine residues in both hESC and tumour cell lines." (PMID 25998442, 2015).
tumor (continued). "Western blot analysis showed that Smad2 phosphorylation was significantly higher in HCT116 tumor microenvironment co-culture compared with HCT116 high density mono-cultures, as seen as broad bands with apparent molecular weights ranging over 58 kDa, which are characteristic of p-Smad2 polypeptides." (PMID 25238234, 2014). "For instance, HIPK2 has been shown to serve as a transcriptional coactivator in the Smad2/3/4-SBE reporter assays and in JNK-mediated functions, which critically regulate the decision of survival and apoptosis in dopaminergic neurons and in tumor cells, respectively." (PMID 23565059, 2013). "In addition, in mRNA levels, the relations between TGF β1 and Smad2, Smad7 were also found (R2=0.12, P=0.059 and R2=0.40, P<0.001, respectively), but none of them correlated to tumor size." (PMID 23151305, 2012). "Since TGF-β is induced by radiation in vitro and in vivo including in the skin and during tumor treatment with radio- and chemotherapy, we tested whether TGF-β signaling was activated in our model by monitoring Smad-2 phosphorylation in skin and HUVEC in response to ionizing radiation." (PMID 20552031, 2010). "However, four tumor markers (POSTN, pSMAD2/3, CXCL14, ADH1B, FAP) that have previously been reported to predict suboptimal debulking were selected in our model, although only p-SMAD2/3 was in the same direction but with lower discriminatory performance compared to prior reports." (PMID 36761962, 2023). "The effects of TAZ on TNBC tumour progression, including also modulation of the immune TME, might therefore be modulated in part via interactions not only with TEADs but also with other transcription factors such as SMAD2/3 or SMAD7, which regulates Treg migration into tumours." (PMID 37716913, 2023). "Our finding that Smyca binds Smad3 but not Smad2 to elevate the expression of pro-tumor effectors of Smad not only is consistent with these previous studies but also suggests Smyca as one factor that contributes to the differential effects of Smad2 and Smad3 on tumor progression." (PMID 35794621, 2022). "Based on these data, we conclude that CRC‐associated downregulation of VPS4B does not reflect its own tumor suppressor function but rather represents a passenger alteration co‐existing with concomitant loss of the neighboring 18q‐located tumor suppressors, such as DCC, SMAD2, and SMAD4." (PMID 31930723, 2020). "The functional relevance of chromosome 18 loss has been discussed longish and controversially with involvement of several tumor suppressors like DCC, Elongin A3, SMAD2, SMAD4, and MIR1-2, but so far, no conclusive results exist." (PMID 40410286, 2025). "Transforming growth factor β1 (Tgfβ1), abundant in the tumor microenvironment (TME), regulates cellular differentiation via the classical Smad2/3 pathway, yet paradoxically fails to drive MDSC maturation." (PMID 41360769, 2025). "TMEPAI, induced by TGF-β1, provides negative feedback on TGF-β1 signaling by interacting with Smad2 and preventing SARA from recruiting Smad2 to TβRI, and hence, suppresses the conical tumor suppressor action of TGF-β1." (PMID 38675493, 2024). "In tumor tissue, we demonstrated a negative correlation between expression of cytoplasmic LINC00707 and phosphorylated Smad2." (PMID 37784093, 2023). "In HCC, EMT plays a crucial role in tumor progression and metastasis and TGF-β1 is a potent inducer of EMT through canonical (Smad2/3 dependent) and non-canonical pathways as we and others have described." (PMID 34638417, 2021). "Immunohistochemical analysis showed tumor cells positive for BMP-2, osteonectin, osteocalcin, AE1/AE3, TGF-β1, Gli2, Smad2/3, and CDX2 and negative for nestin, CD56, and CK7." (PMID 33388078, 2021). "In an in vitro cell model or in vivo tumor tissues, dipyridamole treatment resulted in a decline in the levels of HMGB1, RAGE, β-catenin, Runx2, YAP1, phosphorylated Smad2/3, and cyclin D1, but not TLR2 and TLR4." (PMID 33669632, 2021).
tumor (continued). "Intriguingly, KD of SMAD3, but not SMAD2, in one model with stimulated metastasis (MVT1) increased metastasis, suggesting that SMAD3 has direct anti-metastatic effects on the tumor cell in this model." (PMID 33260366, 2020). "MiR-203/TGF-β/Smad2 expression represents an important tumor suppressor signaling pathway for bone metastasis in NSCLC, as patients with bone metastasis exhibited lower tumor tissue miR-203 expression than those without bone metastasis." (PMID 30813457, 2019). "The results showed that MUC1-C was significantly higher in metastatic IBC than that in non-metastatic tumor, and a positive correlation was found between the expression levels of MUC1-C and SMAD2 protein." (PMID 31399552, 2019). "GDF15 also stimulated the phosphorylation of Smad2, but the GDF15-induced tumor sphere forming efficiency was not significantly affected by treatment with SB431542, an inhibitor of the TGFβ signaling." (PMID 28206960, 2017). "Toxicarioside A altered Smad1 signaling but not Smad2/3 signaling only in HUVECs, not in CT24 or LL/2 tumor cells." (PMID 23209720, 2012). "Moreover, our results support that the tumour-promoting effects associated with the enhanced migration of high SMAD3 fibroblasts could be prevented with Trametinib or other MEK inhibitors in ADC but not SCC, since high SMAD2 fibroblasts as in SCC-TAFs were largely non-responsive to MEK inhibition." (PMID 36572730, 2023). "Similarly to the murine pancreatic KPC3 tumor model, murine colon MC38 tumors display phosphorylated Smad2, but they do not contain many αSMA+ fibroblasts and collagen and show a basal presence of CD8+ T cells." (PMID 36860656, 2023). "Expression of SMAD2/3/4 is increased in i3 cancers but gene signatures related to TGF-beta activity were not consistently different in i3 and i2 tumor cells." (PMID 35773407, 2022). "However, deletion of a number of key TGFβ signaling components (e.g., TGFβ1, TGFBR1, SMAD2/3, and SMAD4) alone in the ovary does not induce tumor formation, challenging TGFβ signaling as essential tumor suppressor in the ovary." (PMID 27344183, 2016). "To further confirm whether or not HS-173 inhibits tumor growth through the regulation of EMT, we identified the expression levels of Ecadherin, Vimentin, ZEB1 along with p-AKT and p-Smad2." (PMID 27793006, 2016). "Notably, 5a-HSA did not reduce nuclear p-SMAD2/3 expression in the adjacent non-neoplastic “healthy” liver, indicating that 5a-HSA could reduce TGFβ activation only in the tumor microenvironment." (PMID 40055773, 2025).
cancer (450 papers, 1998 to 2026). A tumor composed of atypical neoplastic, often pleomorphic cells that invade other tissues. "TGFB1 from cancer cells activated CAFs to produce THBS2 through the p-Smad2/3 pathway, suggesting an important role for TGFB association with THBS2 in cancer progression." (PMID 41373732, 2025). "Dysregulation of SMAD2 is implicated in various pathologies, including fibrosis and cancer, making it a potential target for therapeutic interventions and a biomarker for disease progression." (PMID 39842382, 2025). "The fibroblast cluster showed activation of SMAD2/3 transcription factor activity, which is important for cancer‐associated fibroblasts development and gemcitabine resistance in PDAC." (PMID 38426634, 2024). "In pancreatic ductal adenocarcinoma (PDAC), TGF-β1 secreted from cancer-associated fibroblasts (CAFs) drives the elevation of ATF4 expression through the SMAD2/3 pathway to modulate cancer cell proliferation, migration and stemness." (PMID 39261452, 2024). "Several studies revealed the correlations between mutations of SMAD family proteins (Smad2, Smad3, Smad4 and Smad7) and various diseases and cancers, with the intracellular signal transduction molecule proteins (SMAD) in the TGF-β pathway." (PMID 37742025, 2023). "Though SMAD2 and 3 are rarely mutated in cancers, SMAD4 is lost in about 50% of PDAC, and the role of SMAD2/3 in a SMAD4-null context remains understudied." (PMID 36207615, 2022). "Imbalance in the myostatin—Smad2/3 pathway causes muscle atrophy, which, in the context of cancer, is called cancer cachexia." (PMID 35457038, 2022). "TOP2A silencing reduces the phosphorylation of Smad2 and Smad3 and impairs the malignant characteristics of cancer cells, which is implicated in the carcinogenesis of high-grade serous OC." (PMID 34787052, 2021). "As a result of the loss of heterozygosity (LOH) in the 18q21 region, SMAD2 gene expression is reduced in several cancers and increases cancer progression." (PMID 33672900, 2021). "Stimulated FA oxidation was confirmed by a net increase in the cellular pool of acetyl-CoA in 6.5/cancer cells and associated Smad2 acetylation." (PMID 31974393, 2020). "Smad2/3 activation has been suggested to be closely linked with EMT of cancer cells, while inhibited nuclear translocation of Smad2/3 has been suggested to participate in cancer cell apoptosis." (PMID 32423468, 2020). "Cancer-associated SMAD2 mutations are also defective for SMAD2/SMAD4 complex formation, and cutaneous papillomavirus E6 proteins seem to functionally mimic SMAD2 mutations." (PMID 28107544, 2017). "The activation of Smad2/4 causes the invasion and metastasis of cancer cells by inducing the activity change of E-cadherin." (PMID 27765040, 2016). "Gene deletion and mutation of Smad4 and Smad2 have been identified in certain human cancers and implicated in cancer development." (PMID 22204491, 2011). "Genetically, Smad2 and Smad4 are frequently mutated or deleted in certain human cancers whereas Smad3 mutation or deletion is infrequent." (PMID 22204491, 2011). "In conclusion, periostin from cancer-associated fibroblasts might be associated with the malignant progression of CRC via Smad2/3 signaling." (PMID 39941916, 2025). "Besides SMAD4 and DCC, this region encloses known cancer-related genes that were significantly associated with a higher relapse probability of early-stage primary tumors, namely SMAD2 and BCL2." (PMID 36085309, 2022). "In HCT116_WT, we observed phase-shift transcript pairs from SMAD2, a cancer hallmark gene." (PMID 35552415, 2022).